RN7SKP93 (RN7SK pseudogene 93)
Gene: Miscellaneous RNA gene on chromosome 2 (133,596,091 to 133,596,399, forward strand). Ensembl gene ENSG00000200708.
Homologues: Paralogues in human: RN7SKP255 (77% identical), 7SK (75% identical), RN7SKP203 (75% identical), RN7SKP9 (75% identical), RN7SKP176 (74% identical), RN7SKP204 (74% identical), RN7SKP211 (74% identical), RN7SKP184 (73% identical), RN7SKP189 (73% identical), RN7SKP217 (73% identical), RN7SKP38 (73% identical), RN7SKP180 (73% identical), and 284 more.